CD44 (CD44 molecule (IN blood group))
Diseases named in the same sentence as CD44 in open-access papers (continued):
Sharing a sentence is not in itself a finding about the gene and the disease.
abdominal aortic aneurysm (1 paper, 2025). Enlargement and ballooning of the vessel that supplies arterial blood to the abdomen, pelvis and legs. "Similarly, the protein level of HA receptor CD44 was significantly higher in the human tissue of abdominal aortic aneurysms compared to the control group." (PMID 41280888, 2025).
acute leukemia (1 paper, 2019). A clonal (malignant) hematopoietic disorder with an acute onset, affecting the bone marrow and the peripheral blood. "Acute leukemia blast cells, like human HSCs, differ from neutrophils as they can use PSGL-1, CD44 and/or CD43 to interact with E-selectin." (PMID 31461905, 2019).
acute liver failure (1 paper, 2018). Rapid deterioration of liver function causing encephalopathy and coagulopathy. "Recently, it has been suggested that polymorphisms in the CD44 (rs1467558) and CYP3A5 (rs776746) genes might contribute to risk for paracetamol-induced acute liver failure, in addition to the previously discovered UGT1A-39UTR variant (rs8330)." (PMID 30274302, 2018).
acute monocytic leukemia (1 paper, 2020). Acute monoblastic leukemia (AML-M5), is one of the most common subtypes of acute myeloid leukemia (AML) that is either comprised of more than 80% of monoblasts (AML-M5a) or 30-80% monoblasts with (pro)monocytic differentiation (AML-M5b). "IL-8 and GM-CSF were required in the differentiation of acute monocytic leukemia induced by CD44." (PMID 33193674, 2020).
Acute otitis media (1 paper, 2019). Acute otitis media is a short and generally painful infection of the middle ear. "We observed strong up-regulation of CD44 and of genes related to its role in leukocyte extravasation into the middle ear, during the course of acute otitis media." (PMID 31226944, 2019).
adrenoleukodystrophy (1 paper, 2025). A peroxisomal disorder resulting in cerebral demyelination, axonal dysfunction in the spinal cord leading to spastic paraplegia, adrenal insufficiency and in some cases testicular insufficiency. "Moreover, CD44+ oligodendrocytes have been described in adrenoleukodystrophy, in which it has been hypothesized that there is a cytotoxic effect mediated by CD44 through the hyaluronate matrix." (PMID 40943148, 2025).
adult T-cell lymphoma (1 paper, 2018). "The C-half of OPN may interact with CD44, and this interaction may facilitate the release of the molecule, since it is reported that soluble plasma CD44 levels are closely associated with OPN in adult T-cell lymphoma (ATL) and MTB infection." (PMID 29385060, 2018).
age-related macular degeneration (1 paper, 2021). Age-related loss of vision in the central portion of the retina (macula), secondary to retinal degeneration. "Verteporfin, an FDA-approved drug for age-related macular degeneration, was repositioned in the GCSC context for its capacity to decrease YAP/TEAD transcriptional activity, cell proliferation, CD44 expression and number of tumorsphere-forming CD44+ALDHhigh GCSCs in vitro." (PMID 33810350, 2021).
AIDS (1 paper, 2016). A syndrome resulting from the acquired deficiency of cellular immunity caused by the human immunodeficiency virus (HIV). "The HIV-1 envelope glycoprotein gp41 could up-regulate CD44 in AIDS patients with CM, which ultimately enhances the adhesion and invasion of Cn to BMECs." (PMID 26897523, 2016).
alcohol cirrhosis (1 paper, 2020). "In addition, CD44 has been demonstrated to be involved in the regulation of inflammation in liver disease and is elevated in patients with ALD, including patients with alcoholic steatosis, alcoholic hepatitis and alcohol cirrhosis." (PMID 33262757, 2020).
Amoebiasis (1 paper, 2019). "In addition, the up-regulated DEGs were significantly enriched in 12 pathways such as NF-kappa B signaling pathway including LYN, LY96, CCL4, CD14; ECM-receptor interaction pathway including CD44, COL6A3, COL1A2, FN1 and Amoebiasis pathway including COL1A2, ITGB2, CD14, FN1." (PMID 31355054, 2019).
ampullary adenocarcinoma (1 paper, 2015). "In the present study, variants of CD44 increased in patients with recurrent ampullary adenocarcinoma." (PMID 26572077, 2015). "Whereas CD44s functions as tumor-promoting oncoprotein in early localized ampullary adenocarcinoma, CD44 variants are expressed in advanced cancer and patients with recurrence." (PMID 26572077, 2015). "Immunohistochemistry staining and reverse-transcription polymerase chain reaction (RT-PCR) was used to detect standard and variant forms of CD44 in samples of ampullary adenocarcinoma." (PMID 26572077, 2015). "In an effort to identify predictors of recurrence in patients with ampullary adenocarcinoma, we investigated the clinical value of assessing standard and variant forms of CD44." (PMID 26572077, 2015). "Networks containing CD44 generated from cDNA microarray analysis revealed that the pathways associated with migration had a key role in pancreatic invasion and cancer recurrence of ampullary adenocarcinoma." (PMID 26572077, 2015). "The aim of the present study was to evaluate the expression of CD44 in patients with ampullary adenocarcinoma." (PMID 26572077, 2015). "The standard CD44 (CD44s) isoform was detected in 76 of 98 patients with ampullary adenocarcinoma, and the negative or weak expression of CD44s was correlated with pancreatic invasion, lymphovascular invasion, advanced stage and bone metastasis." (PMID 26572077, 2015).
ampullary carcinoma (1 paper, 2015). "Crosstalk of multiple CD44-related pathways may be critical in ampullary cancer." (PMID 26572077, 2015).
amyloid (1 paper, 2018). "CD44 was localized extracellularly around the amyloid plaques and at Iba1+ cells closely attached to amyloid plaques (insert)." (PMID 30241479, 2018).
and-neck cancer (1 paper, 2025). "The cells were genetically stable, recapitulated genetic changes typical for LHSCCs, and expressed an epithelial cell marker (pan-keratin), as well as a head-and-neck cancer biomarker, CD44 (CD44 expression levels were higher in tumor cell lines, in comparison to normal cells)." (PMID 40940935, 2025).
Aortic dissection (1 paper, 2020). Aortic dissection refers to a tear in the intimal layer of the aorta causing a separation between the intima and the medial layers of the aorta. "Very recently, CD44 which is the main receptor for extracellular matrix proteins such as hyaluronan, was found to promote adhesion of leukocytes to endothelial cells and participate in the development of aortic dissection." (PMID 32664652, 2020).
Ataxia (1 paper, 2019). Ataxia refers to impaired coordination of voluntary muscle movement. "To assess whether disease development in Malt1-PD and -PDT mice was due to the same mechanism, we evaluated cytokine production by CD44+ CD4+ T cells in cervical lymph nodes (cLN) of mice already suffering from ataxia." (PMID 31474984, 2019).
autoimmune thyroid disease (1 paper, 2020). Inflammatory disease of the thyroid gland due to autoimmune responses leading to lymphocytic infiltration of the gland. "In addition, a study about Graves’ disease (GD) showed that the injection of GD lymphocytes into thyroid tissue transplants increased the expression of CD44 significantly, indicating the important role of CD44 in the pathology of autoimmune thyroid diseases." (PMID 32500465, 2020).
brain injury (1 paper, 2020). Acute and chronic (see also brain INJURIES, CHRONIC) injuries to the brain, including the cerebral hemispheres, CEREBELLUM, and brain STEM. "Osteopontin (OPN) is a complex adhesion protein and cytokine that interacts with multiple receptors including integrins and CD44 variants, exhibiting mostly neuroprotective roles and showing therapeutic potential for acute brain injury." (PMID 32657030, 2020).
candida infection (1 paper, 2018). "In addition, CD44 expression was unaltered by candida infection, indicating, a candida independent and E2-dependent effect." (PMID 29881378, 2018). "However, unique to the lower FRT mucosa, epithelial CD44 and CD47 expression was independent on the candida infection, because neutrophil infiltration and functions must be timed to the ovarian cycle." (PMID 29881378, 2018).
cervical intraepithelial neoplasia (1 paper, 2024). "Therefore, we conducted a retrospective study, consecutively recruiting 113 patients with invasive cancer, 92 patients with high-grade cervical intraepithelial neoplasias, and 302 control women to assess the relationships among CD44 polymorphisms, cervical carcinogenesis, and patient survival." (PMID 38903932, 2024).
Chagas disease (1 paper, 2011). A parasitic infection caused by Trypanosoma cruzi. "Interestingly, despite the expansion of peripheral DP lymphocytes in the experimental model of Chagas disease, these cells develop an activated phenotype, upregulating the activation markers CD44 and CD69, tightly linked to the differentiation status of T cells." (PMID 21858238, 2011).
Chlamydia infection (1 paper, 2024). "Similarly, Chlamydia infection did not lead to a reduction in CD44 protein expression." (PMID 39467689, 2024).
chorioamnionitis (1 paper, 2025). A morphologic finding indicating inflammation of the fetal sac membranes. "In addition, if our results are confirmed by larger population studies, we can attempt to develop local or systemic anti-CD44 and anti-OPN agents to try to control the severity of the host immune response during chorioamnionitis." (PMID 40243431, 2025).
chronic asthma (1 paper, 2025). An asthma that is characterized by the development of persistent airway inflammation and recurrent attacks of breathlessness and wheezing, which vary in severity and frequency. "Gal-9 specifically binds to CD44 and negatively regulates CD44-HA interactions, reducing allergic inflammation in cases of chronic asthma." (PMID 40134029, 2025).
Chronic colitis (1 paper, 2022). A chronic inflammatory disease of the large intestine (colon, cecum and rectum). "Remarkably, it was found a decline in both activated (CD44 +) T CD4 and T CD8 cells in the MLN of mice with chronic colitis compared to controls, suggesting their mobilization to the lamina propria." (PMID 35705557, 2022).
cocaine addiction (1 paper, 2025). "CALM3 and JUN were downregulated in the cocaine addiction group compared to controls (p < 0.05), whereas CCL2, CD44, CLIC1, and VCAM1 were upregulated (p < 0.05)." (PMID 41465087, 2025). "The strong positive correlations observed between genes like CCL2, CD44, and CXCL8 further suggest coordinated regulation of immune processes in cocaine addiction, which may be modulated by exercise." (PMID 41465087, 2025).
craniopharyngioma (1 paper, 2024). A benign, partly cystic, epithelial tumor of the sellar region, presumably derived from Rathke pouch epithelium. "In conclusion, in our current work, we observed for the first time that increased expression of CD44, specifically the CD44s isoform, is associated with the recurrence of craniopharyngioma." (PMID 39020106, 2024). "Nevertheless, further large-scale studies are needed to confirm our results, as are additional preclinical studies to elucidate the exact mechanism of CD44 expression in children with craniopharyngioma who develop recurrence after radical surgical resection." (PMID 39020106, 2024). "CD44 is also a known stem cell marker in craniopharyngiomas." (PMID 39020106, 2024). "Determining the expression of individual CD44 isoforms may be a useful prognostic marker in the assessment of craniopharyngioma recurrence in children." (PMID 39020106, 2024).
cutaneous squamous cell carcinoma (1 paper, 2015). "Recent results indicate that UV irradiation (UVR)-induced cutaneous squamous cell carcinomas (SCC) overexpress a variety of CD44 variant isoforms (CD44v), with different CD44v isoforms appear to confer malignant SCC properties." (PMID 26029210, 2015).
cystitis (1 paper, 2021). Inflammation of the urinary bladder. "In addition, RHAMM as a regulator of CD44–ERK-1/2 fibroblast signalling, is required for mucosal regeneration and to improve urothelial lining defects in cystitis rats." (PMID 34975473, 2021).
deafness (1 paper, 2023). An inherited or acquired condition characterized by the complete loss of the ability to hear from one or both ears. "KIAA1199 was originally identified as a deafness gene and, subsequently, was found to play crucial roles in HA-degrading activities in chondrocytes, independent from HYAL1 and 2 and CD44." (PMID 37569797, 2023).
Desminopathy (1 paper, 2024). "The common hub genes in desminopathy and titinopathy were cytoskeleton- (ACTB, ANXA2), and ECM-related (CD44)." (PMID 39239540, 2024).
dysplastic nevi (1 paper, 2013). "The intensity of stromal CD44 staining was strong in benign and dysplastic nevi, all other lesions showing reduced staining intensity compared to benign nevi (p=0.010-0.000)." (PMID 23560496, 2013).
Erythema (1 paper, 2017). Redness of the skin, caused by hyperemia of the capillaries in the lower layers of the skin. "It was also found that the OHE treatments inhibited the compensatory increases of HA, HABP and CD44 protein expression in hairless mice irradiated with UV, and suppressed the transepidermal water loss and erythema formation." (PMID 28183235, 2017).
esophageal tumors (1 paper, 2011). "In the present study we show that CD44 upregulation is associated with E-cadherin loss in primary esophageal tumor tissues and cancer cell lines." (PMID 22069487, 2011).
Fibroadenoma (1 paper, 2011). A benign tumor of the breast characterized by the presence of stromal and epithelial elements. "We have identified the methylation of five cancer-related CpG islands in the giant fibroadenoma tissue: ESR1, MGMT, WT-1, BRCA2 and CD44." (PMID 22011321, 2011).
Follicular Cyst (1 paper, 2023). Cyst due to the occlusion of the duct of a follicle or small gland. "FGF7 regulated the PPAR signaling pathway (FABP5 and SCD) and the MAPK signaling pathway (FGF1, FGFR2, IL1A, TGFB1, and CSF1) and pathways in cancer (IL7, CD44, SMAD2, and MMP2) may be involved in the formation of follicular cysts." (PMID 38274662, 2023).
Gastric Metaplasia (1 paper, 2025). Intestinal metaplasia of the gastric mucosa is an intermediate precancerous gastric lesion in the gastric cancer cascade from chronic gastritis and atrophy to dysplasia and adenocarcinoma. "In addition, markers of gastric metaplasia, including Tff2, Cd44, and Clu, were upregulated in Arid1a-mutated SPGs, PPGs, and even mature pit cell clusters." (PMID 40761291, 2025).
gastrointestinal lymphoma (1 paper, 1993). A non-Hodgkin or Hodgkin lymphoma that arises from any part of the digestive system, with the bulk of the disease localized to that site. "We conclude that lack of lymphocyte homing receptor expression is common in gastrointestinal lymphoma, and that CD44 expression is associated with unfavourable prognosis." (PMID 8347502, 1993).
giant cell tumor of bone (1 paper, 2015). "This research aimed to study the role of ezrin, CD44, and VEGF in invasion, metastasis, recurrence, and prognosis of giant cell tumor of bone (GCTB) and its association with the clinical and pathological features of GCTB." (PMID 25929323, 2015).
heart transplant (1 paper, 2010). "We found that PECAM1, CXCL9 and CD44 proteins were significantly upregulated in the serum/plasma samples of both renal and heart transplant patients with acute rejection compared with patients with stable graft function." (PMID 20885780, 2010).
hemangiosarcoma (1 paper, 2010). "On the other hand, expression of PDGFRβ, CD44, and EPHA2 in hemangiosarcoma cell lines was not predictive for the expression of these proteins in tumor tissues, and a similar trend was observed for Neuropilin 1 and v-Myc." (PMID 21062482, 2010).
herpes zoster (1 paper, 2025). A common dermal and neurologic disorder caused by reactivation of the varicella-zoster virus that has remained dormant within dorsal root ganglia, often for decades, after the patient's initial exposure to the virus in the form of varicella (chickenpox). "Furthermore, CVE markedly outperformed Shingrix in inducing CD8+ tissue-resident memory T cells (TRMs, CD44+CD62L-CD103+), a population essential for mucosal barrier defense and prevention of herpes zoster reactivation." (PMID 41441692, 2025).
histiocytic lymphoma (1 paper, 2017). "Since this line of histiocytic lymphoma does not express HAS2, the hyaluronan receptor CD44 was investigated, as this receptor is commonly expressed." (PMID 29023465, 2017). "However, in histiocytic lymphoma that constitutionally does not express HAS2, when CD44 mRNA was tested upon treatment with Apixaban to explore the hyaluronan receptor expression, CD44 was reduced by drug treatment." (PMID 29023465, 2017).
idiopathic pulmonary arterial hypertension (1 paper, 2021). A sporadic form of pulmonary arterial hypertension (PAH) characterized by elevated pulmonary arterial resistance leading to right heart failure. "This suggests that CD44 is involved in the pathogenesis of idiopathic pulmonary arterial hypertension." (PMID 34335086, 2021).
IgG4-related disease (1 paper, 2019). "Indeed, plasmablasts of IgG4-related disease patients express increased RNA levels of CD44 and SDC1 associated with cell migration and increased surface marker levels of activation markers such as HLA-DR, CD95." (PMID 31608054, 2019).
ileitis (1 paper, 2017). "For example, gene networks associated with ileitis were suppressed ~8% (P < 0.05), and included Cd36, Il4, Cd44, Cd4, and Cd40." (PMID 28446880, 2017).
infarction (1 paper, 2024). A localised pathological necrosis of tissue resulting from obstruction of the blood supply usually by a thrombus, an embolus, or vascular torsion. "Likewise, more Iba1+/CD44+/OPN+ cells were identified in the affected WM (183.05 ± 133.3/mm2) as compared to the WM contralateral to infarction (2.4 ± 3.02/mm2) and the comparison to Sham WM (3.1 ± 2.6/mm2) approached statistical significance." (PMID 39043661, 2024).
infectious arthritis (1 paper, 2025). "Its clinical presentation is similar to infectious arthritis, but its mechanism is known to be related to high production of proinflammatory cytokines and hypersensitivity reactions; hyaluronan and CD44 have a ligand-receptor association that may increase the recruitment of inflammatory cells." (PMID 40069683, 2025).
interstitial nephritis (1 paper, 2015). Inflammation of the renal tubules and supporting tissues of the kidney. "In interstitial nephritis sites where HA is increased, HA receptor CD44 is expressed in high levels suggesting in vivo interaction of HA and CD44." (PMID 26448753, 2015).
intimal sarcoma (1 paper, 2019). A malignant neoplasm arising from the large blood vessels. "Recent studies also reported that PDGFRα and CD44 were positive in intimal sarcoma." (PMID 30925179, 2019).
invasive carcinoma (1 paper, 2023). A carcinoma that is not confined to the epithelium, and has spread to the surrounding stroma. "More than 50% of invasive carcinomas and CIN2+ lesions had decreased CD44 expression, which may be related to loss of cellular adhesion." (PMID 36768853, 2023).
joint disease (1 paper, 2023). "A key feature in the development of joint disease is the overexpression of adhesion molecules, e.g., CD44." (PMID 37895896, 2023).
kidney failure (1 paper, 2019). An acute or chronic condition that is characterized by the inability of the kidneys to adequately filter the blood. "Indeed, Axin2, Cd44, Ccnd1 and to certain extent Myc, showed significantly lower expression in double KO compared with Pkd1 KO mice, both at 10 weeks after DCVC and at kidney failure, suggesting a reduced activation of the canonical Wnt signalling in the absence of Fjx1." (PMID 31038742, 2019).
kidney tumors (1 paper, 2022). "Lin, CD11b, CD33, and CD44 were hypomethylated, while CD55 was hypermethylated in RMCs compared to the other kidney tumors." (PMID 36291828, 2022).